NLRP3 (NLR family pyrin domain containing 3)
Diseases named in the same sentence as NLRP3 in open-access papers (continued):
Sharing a sentence is not in itself a finding about the gene and the disease.
colitis (continued). "Extracellular ADP activates NLRP3 inflammasomes via P2Y1 receptor-mediated calcium signaling, and deletion of P2Y1 receptors or treatment with P2Y1 receptor inhibitors inhibits NLRP3 inflammasomes activation to alleviate colitis." (PMID 36590401, 2022). "Lack of negative regulation by IL-10 leads to NLRP3 overactivation in Il10−/− mice that develop spontaneous colitis." (PMID 34344313, 2021). "Recent studies have illustrated that excessive NLRP3 inflammasome–induced IL-1β aggravates colitis, and the absence of NLRP3 inflammasome components has a protective role in the dextran sodium sulfate (DSS)-induced colitis model." (PMID 34322027, 2021). "In this model the pro-inflammatory role of IL-1β seems to be non-redundant as treatment with a CASP1 or a NLRP3 inhibitor ameliorated established disease and prevented or delayed development of spontaneous colitis." (PMID 34344313, 2021). "Considering the amount of IL-1β secreted in the distal colon of Winnie mice together with our earlier results that a small molecule inhibitor of the NLRP3 inflammasome ameliorates colitis in Winnie mice, it is possible that UTA77 also prevents NLRP3 inflammasome activation." (PMID 34497514, 2021). "find that mice lacking Nlrp3 are more susceptible to both acute and intermittent DSS-induced colitis and AOM/DSS-induced colitis-associated CRC." (PMID 35111698, 2021). "Depending on the animal model, environment and hygienic conditions, lack of NLRP3 either ameliorated or aggravated experimental colitis." (PMID 34344313, 2021). "Curcumin could significantly inhibit the activation of NLRP3 inflammasome in DSS-induced mice, reduce the expression of IL-1, IL-6, and other inflammatory cytokines, and alleviate the symptoms of colitis in DSS-induced mice." (PMID 34055024, 2021). "Data from murine models of experimental colitis with animals lacking NLRP3 show diverging effects depending on the model, experimental conditions and environment." (PMID 34344313, 2021). "AMPK inhibitor (Dorsomorphin, 10 mg/kg) not only suppressed p-AMPK and Nrf2 protein expression levels, but also induced NLRP3 and Caspase-1 protein expression levels in DSS-induced colitis mice treated with Schisandrin B, in comparison to the group treated with Schisandrin B." (PMID 34628369, 2021). "Moreover, TRIM31 was found to suppress the activation of NLRP3 inflammasome by promoting NLRP3 polyubiquitination and proteasome degradation, thus alleviating DSS-induced colitis." (PMID 34956195, 2021). "NF-kappaB signaling and consequent NLRP3 inflammasome activation have been shown to be suppressed by fraxinellone, a lactone compound, and by alpinetin, a novel plant flavonoid; both alleviate DSS-induced colitis." (PMID 34064909, 2021). "Thus, palmatine inhibited DSS-induced colitis by promoting PINK1/Parkin mediated mitophagy, and consequently the inactivation of the NLRP3 inflammasome in macrophages." (PMID 33808793, 2021). "E. faecalis administration ameliorated DSS-induced colitis and CRC in wild-type mice, while this effect was not seen in NLRP3-deficient mice." (PMID 33808793, 2021). "Importantly, in vivo experiments demonstrated that administration of echinatin obviously inhibits NLRP3 inflammasome activation and ameliorates LPS-induced septic shock and dextran sodium sulfate–induced (DSS-induced) colitis in mice." (PMID 33350984, 2021). "Some of this evidence suggests that after colitis occurs, the production of IL-1β, IL-18, and anti-inflammatory cytokines IL-10 and TGF-β decreases in Nlrp3−/− mice, which may in turn hinder repair mechanisms and increase intestinal epithelial permeability." (PMID 33227973, 2020). "Drugs targeting NLRP3 inflammasome and autophagy to treat colitis are absent, and they are urgently required." (PMID 33240089, 2020). "For instance, numerous studies have shown that attenuation of DSS-colitis, a closely related disease to PSC, might be achieved by repressing the NLRP3 inflammasome." (PMID 32716024, 2020).
colitis (continued). "A previous study has demonstrated that dimethyl fumarate (DMF) protects mice from dextran sulfate sodium (DSS)-induced colitis via its potential antioxidant capacity, and by inhibiting the activation of the NOD-, LRR- and pyrin domain-containing protein 3 (NLRP3) inflammasome." (PMID 32344663, 2020). "This suggests that, consistent with the pro-inflammatory role of NLRP3 and IL-1β in intestinal inflammation, the E. faecalis pretreatment-induced attenuation of NLRP3 inflammasome activity in macrophages can ameliorate DSS-induced colitis." (PMID 30823406, 2019). "The same experiment was performed in inflammasome Nlrp3-/- mice, and the results showed that dietary TiO2 at 500 mg.kg−1 did not reproduce colitis exacerbation in Nlrp3/- compared to the response of the wild type mice." (PMID 31109097, 2019). "However, mouse models of colitis show improvement in the presence of CB2 through apoptosis of T-cells and through inhibition of the NLRP3 inflammasome in macrophages." (PMID 30196316, 2019). "The levels of cleaved (activated) caspase-1 and mature IL-1β were reduced by E. faecalis in the colon tissues of mice with DSS-induced colitis compared to PBS control in wild type mice, but not in NLRP3-deficient mice." (PMID 30823406, 2019). "The aim of this study was to systematically identify possible hierarchical regulatory role of inflammasome components, including NLRP3 and NLRP1, and the activation of the Th-17 pathway in the luteolin- and wedelolactone-mediated suppression of DSS-induced colitis." (PMID 30297787, 2018). "Importantly, inhibition of Cbl with the pharmacological inhibitor, hydrocotarnine, enhances NLRP3 inflammasome activation and protects mice from DSS-induced colitis." (PMID 30382081, 2018). "Complete inhibition with MCC950 in Winnie colonic explants shows, for the first time, the contribution of inflammatory effects resulting exclusively from canonical and noncanonical NLRP3 inflammasome activation in colitis." (PMID 29872077, 2018). "TCDD ameliorated colitis symptoms by suppressing Th17 cell differentiation, resulting in decreased IL-17 and IFN-γ expression, while NOR reduced colitis by promoting Treg differentiation and inhibiting the NLRP3 inflammasome." (PMID 30513921, 2018). "DCA induces NLRP3 inflammasome activation mainly via promoting cathepsin B release and colorectal instillation of DCA could significantly exacerbate DSS-induced colitis through activating NLRP3 inflammasome." (PMID 29854830, 2018). "Activation of the NLRP3 inflammasome has also been shown to be critically involved in maintaining epithelial integrity in the colon and attenuating dextran sulfate sodium (DSS)-induced colitis in mice." (PMID 30382081, 2018). "Our results show, for the first time, the contribution of anti-inflammatory effects resulting exclusively from inhibition of canonical and non-canonical NLRP3 inflammasome activation in colitis." (PMID 29872077, 2018). "The results indicate that TRAIL reduces the induction of colitis and the initiation of CAC by inhibiting pro-inflammatory signaling and promoting tissue repair to maintain intestinal homeostasis through activation of the NLRP3 inflammasome." (PMID 29416724, 2018). "This is an important finding as this indicates the percentage of canonical and non-canonical NLRP3 inflammasome contribution to the overall IL-1β in the spontaneous colitis colon of Winnie mice." (PMID 29872077, 2018). "Furthermore, the results in vivo demonstrate that alpinetin markedly attenuates DSS-induced acute colitis through TLR4 and NLRP3 pathways." (PMID 30166541, 2018). "The protective role of caspase-11-induced non-canonical NLRP3 inflammasome activation has been shown in a model of Gram-negative C. rodentium infection-induced colitis." (PMID 28179906, 2017).
colitis (continued). "With regard to non-canonical NLRP3 inflammasome activation, the majority of current data suggest that caspase-11-dependent NLRP3 activation, although dispensable for caspase-1-inflammasome assembly, contributes to protection against DSS-induced colitis regulating the epithelial barrier integrity." (PMID 28179906, 2017). "Moreover, our in vivo data showed that procyanidin attenuated Dextran sulfate sodium-induced experimental colitis in a dose-dependent fashion by suppressing the expression of MMP9, NF-κB, and NLRP3 inflammasome signaling in colonic tissues in mice." (PMID 29354126, 2017). "In the present study, we examined the anti-inflammatory effect of procyanidin in dextran sulfate sodium (DSS)-induced colitis and found that procyanidin decreased the generation of ROS, inhibiting the expression of MMP9, NF-κB, and formation of the NLRP3 inflammasome." (PMID 29354126, 2017). "Interestingly, hypoxia downregulated NLRP3 concomitantly with the induction of autophagy in the DSS and Il-10−/− mouse models of colitis, suggesting a role for NLRP3 in hypoxia-induced autophagy." (PMID 28740109, 2017). "MOS administration attenuated colitis-related increase of Coliforms, normalized colonic muc2 expression and attenuated local expression of proinflammatory cytokines IL-1a, IL1b, IL6, KC, G-CSF and MCP1 as well as toll-like receptor TLR4 and NLRP3 inflammasome." (PMID 27658624, 2016). "Furthermore, caspase-12−/− mice, which exhibit increased NLRP3 inflammasome signaling, were protected from DSS-induced colitis." (PMID 27610005, 2016). "Although there are controversies about the role of NLRP3 inflammasome during the process of colitis in various knockout mice, many studies has proved that pharmacological blockage of NLRP3 activation and/or NF-kB can obviously ameliorate DSS colitis." (PMID 27105502, 2016). "It should be also emphasize that in vivo, when using bone marrow chimeras the DSS-induced colitis protective effect was shown to be due NLRP3 signaling in non-hematopoietic cells." (PMID 25822487, 2015). "Similar phenotypes have been observed in caspase-1–deficient mice, and also in mice deficient in the canonical inflammasome components, NLRP3 and ASC, suggesting that the noncanonical inflammasome is activated in vivo during acute DSS-colitis." (PMID 25548224, 2015). "Our findings demonstrate the NOD2-RIP2 pathway helps suppress the non-canonical NLRP3 inflammasome in vivo during C. rodentium induced colitis." (PMID 25254654, 2014). "The tumor-suppressing function of inflammasomes does not always correlate with their role in promoting or suppressing DSS-induced inflammation; rather some studies have reported that Casp1−/− and Nlrp3−/− mice have decreased DSS-induced inflammation and colitis." (PMID 24474192, 2014). "Additionally, homozygous knock-out of NLRP3 and caspase-1 genes, or inhibition of caspase-1 by a specific inhibitor, protects mice from DSS-induced colitis." (PMID 23915129, 2013). "Therefore, we concluded that activation of NLRP3 inflammasome during colitis is dependent on the interaction of TXNIP and NLRP3, and that this activation is mediated by mtROS." (PMID 23915129, 2013). "Models of experimental colitis have shown that macrophages promote crypt proliferation and that NLRP3 inflammasome production of IL-18 (not IL-1β) is required for epithelial protection." (PMID 24312491, 2013). "We gavaged high-dose TiO2 NPs daily to NLRP3−/− mice with DSS-induced colitis and found that the absence of NLRP3 improved the anti-oxidative ability of the liver, which was manifested by a decreased MDA content, enhanced SOD activity, and increased GSH content." (PMID 41008252, 2025). "Thus, similar to NLRP3, lncOlfr29 promotes sensitivity to DSS-induced colitis." (PMID 40933997, 2025).
colitis (continued). "RRx-001 interacts with C409 of NLRP3 and suppresses the interaction of NLRP3 with NEK7, thereby inhibiting inflammasome assembly and alleviating symptoms in various disease models, including systemic inflammation, colitis, and experimental autoimmune encephalomyelitis in mice." (PMID 40307577, 2025). "Mice lacking NLRP3 are more prone to dextran sodium sulfate-induced colitis." (PMID 41149694, 2025). "Similarly, preclinical studies indicate that compounds like Polyphyllin VI and HMB can regulate macrophage polarization through specific pathways such as the autophagy-NLRP3 axis and ERK/NF-κB pathway to alleviate colitis, highlighting these mechanisms as potential intervention targets." (PMID 41150761, 2025). "Furthermore, colitis aggravation and NLRP3 stimulation were seen in animals lacking the miR-223 binding region in the NLRP3 3′ UTR." (PMID 39259390, 2024). "The NLRP3 inflammasome (NOD-, LRR- and pyrin domain protein 3) is the most studied, an intracellular polymeric protein signaling complex that participates in the innate immune system and plays an important role in maintaining intestinal homeostasis and preventing colitis." (PMID 39185411, 2024). "In addition, the protective role of A. muciniphila in colitis was abolished in mice lacking the NLRP3 gene." (PMID 39323474, 2024). "In addition, E. faecalis does not protect NLRP3 knockout mice from developing colitis when exposed to DSS." (PMID 39323474, 2024). "This paradox is further supported by findings that demonstrate mouse models of chemically-induced colitis and immune-mediated biliary inflammation have an exaggerated immune response in the absence of NLRP3, suggesting that NLRP3 also displays tissue-protective functions." (PMID 38842647, 2024). "Bauer and collaborators demonstrated a critical role of NLRP3 inflammasomes in intestinal inflammation in the DSS colitis model, since NLRP3-deficient mice developed mild colitis, unlike WT mice, and the levels of pro-inflammatory cytokines in colonic tissue were reduced." (PMID 39684769, 2024). "Thus, LMP2-specific inhibitor YU102 downregulates activation of the NLRP3 inflammasome by decreasing NLRP3 protein levels without altering immunoproteasome expression in the DSS-treated colitis model mice." (PMID 38667290, 2024). "There is evidence that suppression of NLRP3-inflammasome activity reduces both apoptosis and pyroptosis of mesenchymal stromal cells (MSC) in three-dimensional culture and improves the therapeutic efficacy of transplanted MSC spheroids in a mouse model of colitis." (PMID 39539344, 2024). "Additionally, the NLRP3 (NOD-, LRR-, and pyrin domain-containing protein 3) inflammasome is a well-studied protein complex involved in the progression of numerous inflammatory diseases, including DSS-induced colitis." (PMID 37107245, 2023). "Recently, a number of independent studies suggested that proper intracellular NLRP3, Caspase-1, ASC and IL-1β levels are a prerequisite to maintain intestinal epithelial integrity, limit pathogen colonization and prevent systemic dispersion of commensal bacteria and severe colitis." (PMID 37891577, 2023). "In addition, this study also showed that the other mechanisms triggering NLRP3 inflammasome activation, like ROS generation, K+ efflux and cathepsin B leakage, could be suppressed in DSS-induced colitis after curcumin treatment." (PMID 37833958, 2023). "Animal and human studies have revealed that the role of the NLRP3 inflammasome in the pathogenesis of IBD remains unclear; in this study, we found that hyperactivation of intestinal NF-κB and NLRP3 aggravated experimental colitis in mice." (PMID 37292154, 2023). "constructed mouse models of peritonitis and colitis and demonstrated that 1′-acetoxychavicol acetate (ACA; a natural compound in the rhizome of tropical ginger) inhibited mtROS production and mtDNA oxidation to reduce NLRP3 inflammasome activation, thereby alleviating the colitis in mice." (PMID 37533869, 2023).
colitis (continued). "Baicalein attenuated TNBS-induced colitis, at least in part, by inhibiting the TLR4/MyD88 signaling cascade (NF-κB and mitogen-activated protein kinase (MAPK)) and inactivating nucleotide-binding oligomerization domain-like receptor pyrin domain containing 3 (NLRP3) inflammasome." (PMID 36768278, 2023). "Considering that IL−1β and IL−18 were important NLRP3 inflammasome−dependent cytokines, and that the BUR treatment could reduce the release of these two inflammatory mediators, we then explored whether BUR inhibited NLRP3 inflammasome activation in colitis." (PMID 36290717, 2022). "Thus, the anti-colitis role of NOR is mediated by inhibiting the NLRP3 inflammasome activation via modulating AhR/Nrf2/ROS pathway." (PMID 36090968, 2022). "NLRP3 can be initiated by transcription factor nuclear factor-kappa B (NF-κB) as the first step of pyroptosis, and also, NF-κB can be activated by the mitogen-activated protein kinase (MAPK) pathway; both of them regulate the balance between mucosal homeostasis and inflammation in colitis." (PMID 36120344, 2022). "Furthermore, intestinal barrier dysfunction in DSS-induced colitis in mice allows the translocation of bacteria to stimulate lamina propria Mø via TLR/NF-κB, leading to pro-IL-1β and pro-IL-18 transcription, consequently NLRP3 activation." (PMID 36466902, 2022). "The sequel of events triggered by TLR-4 activation, including NF-kB and NLRP3 activation, and the release of IL-1β, IL-6, and TNF-α, are considered the most involved in persistent intestinal inflammation triggering and maintenance during colitis, and HIV-1 Tat-induced diarrhea." (PMID 36009057, 2022). "Furthermore, activated nuclear factor-erythroid factor 2-related factor 2 (Nrf2), the primary regulator of the antioxidant response, can inhibit the assembly of the NLR family pyrin domain containing 3 (NLRP3) inflammasome, thereby preventing dextran sulfate sodium (DSS)-induced colitis." (PMID 36339623, 2022). "Regulation of the NLRP3 inflammasome using herbal compounds can affect the development of colitis via multiple mechanisms, whereas previous studies have shown that other inflammasome forming NLRs such as NLRP1, NLRP6, NLRC4 and AIM2 are also involved in the pathogenesis of colonic inflammation." (PMID 36090968, 2022). "Therefore, E. faecalis might have a potential therapeutic use in inhibiting colitis and CRC by modulating NLRP3 inflammasome activation." (PMID 33808793, 2021). "Our results indicated that OCOP eminently alleviated acute colitis elicited by DSS, which exhibited similar anti-UC effect to the reference drug mesalazine (MSZ) with much smaller dosage and superior to COP via regulation of NF-κB pathway and NLRP3 inflammasome." (PMID 33859564, 2021). "Similar to P. mirabilis, the lack of NLRP3 or the blockade of IL‐1 signaling cancels the colitogenic effect of K. aerogenes, suggesting the central role of the NLRP3–IL‐1β axis in the pathogenesis of oral commensal pathobiont‐driven colitis." (PMID 34705319, 2021). "However, other studies do not support this research, whereby two studies failed to confirm the protective role of NLRP3 against DSS-induced colitis." (PMID 34571825, 2021). "In addition, a non-cytotoxic, acrylate-based NLRP3 inhibitor (INF39) was successfully developed that attenuated colitis through irreversible inhibition of the NLRP3 ATPase activity." (PMID 32456012, 2020). "In vivo, Cg-induced colitis was reduced in mice in the absence of NLRP3 inflammasome components." (PMID 32894139, 2020). "During the onset of DSS-induced colitis, CD14/TLR4:LPS-dependent interaction between macrophages and bacteria, which have passed through DSS-injured colonic epithelium, results in the activation of NLRP3 inflammasome, which leads to the enhanced production of IL-1β in colonic macrophages." (PMID 31336879, 2019).